IGF1 (insulin like growth factor 1)
Diseases named in the same sentence as IGF1 in open-access papers (continued):
Sharing a sentence is not in itself a finding about the gene and the disease.
growth failure (56 papers, 2008 to 2025). "In prior studies, it has been shown that children with CP who have a growth deficiency have low levels of growth hormone (GH) and Insulin Growth Factor-1 (IGF-1) and are insufficiently responsive to insulin stimulation." (PMID 39201827, 2024). "Growth retardation is linked to reduced vitamin A consumption because it lowers IGF-1 serum production, which triggers the release of nocturnal growth hormone." (PMID 37663225, 2023). "Here, we document IGF-1 effects on coronary atherosclerosis in FH pigs, using recombinant human IGF-1 at a dose that is FDA approved for long-term treatment of growth failure in children with severe primary IGF-1 deficiency." (PMID 36602878, 2023). "According to mechanistic studies, insulin is one of the main regulators of growth hormone (GH)/insulin-like growth factor 1 (IGF-1) axis, frequently involved in growth failure associated with several chronic conditions including CF." (PMID 35358060, 2022). "Isolated growth hormone deficiency (GHD) is defined by growth failure in combination with retarded bone age, low serum insulin-like growth factor-1, and insufficient GH peaks in two independent GH stimulation tests." (PMID 33140249, 2020). "In mice that have combined KO of ghr and igf1, the growth deficiency is significantly more severe than in each individual KO, indicating that GH has growth mediating effects that are independent of IGF-1." (PMID 29487568, 2018). "Recombinant human IGF-1 (mecasermin) was developed for the treatment of children with growth failure because of deficient IGF-1 liver production due to mutations or deletion of the hepatic growth hormone receptor." (PMID 28954393, 2017). "IGF-1 is already indicated in the pediatric population for severe growth failure and IGF-1 deficiency." (PMID 27746717, 2016). "Therefore, rhGH would be expected to improve bone growth and height if growth deficiency in KS2 can indeed be attributed towards reduced IGF1, as our data suggest." (PMID 38857303, 2024). "Prior to the discovery of the JAK1GOF variant, patient III-1 underwent clinical evaluation for growth failure, and the growth hormone (GH) signaling axis was assessed by measuring serum levels of insulin-like growth factor (IGF-1), which is produced by the liver in response to GH." (PMID 36546480, 2022). "Collectively, our results support the therapeutic impact of IGF-1 to improve bone strength and density, but suggest that its clinical efficacy may differ depending on the sex of the patient with postnatal growth deficiency." (PMID 33919940, 2021). "The first is clinically characterized by severe postnatal growth failure and facial dysmorphism, and biochemically by normal-to-elevated circulating GH concentrations but deficiencies in circulating Insulin-like Growth Factor 1 (IGF-1) and Insulin-like Growth Factor Binding Protein 3 (IGFBP-3)." (PMID 29025428, 2017). "The child with a history of: growth failure or a documented growth deceleration, associated with: nystagmus or impaired vision and reduced serum concentrations of IGF-1 and IGFBP-3 should be considered GH deficient (or GH-inhibited), even with normal provocative tests." (PMID 20108502, 2008). "While IGF-1 is commonly used as an indicator to screen for GH deficiency in children with growth failure or short stature, our findings suggest that IGF-1 levels may be less accurate for detecting GH deficiency in underweight and obese children, which may result in misdiagnosis." (PMID 37111069, 2023). "In children with growth retardation, lower aBMDHAZ Z-scores were observed in those with decreased IGF-1." (PMID 40364018, 2025). "Our study shows significant inverse relationships between the SIRT1 concentration and the IGF-1 levels, the IGF-1/IGFBP-3 molar ratio and the degree of growth deficiency." (PMID 39062007, 2024).
growth failure (continued). "Given the reports of reduced circulating concentrations of GH and IGF-1 in children with LPI that also suffer from growth failure, we assessed the plasma concentrations of IGF-1 in our Slc7a7Lbu/Lbu mouse model." (PMID 37486182, 2023). "Previous studies have shown that children with CP with growth failure had low basal growth hormone (GH) and Insulin Growth Factor-1 (IGF-1) and responded inadequately to the insulin stimulation test." (PMID 35115566, 2022). "The pathophysiology of postnatal growth failure is complex and involves a variety of alterations in the growth hormone (GH)/insulin-like growth factor (IGF)-1 axis." (PMID 32265840, 2020). "In summary, this is the first study investigating in detail CNVs in subjects with growth failure associated with GHI and IGF-1 insensitivity." (PMID 33055295, 2020). "In this regard, in a recent study, reduced BCAAs levels were found in two siblings with growth failure due to a pregnancy-associated plasma protein A2 (PAPP-A2) gene mutation, which results in less IGF-1 bioactivity and increased GH secretion." (PMID 31561638, 2019). "We describe a 13-month old girl with severe growth failure who showed a low GH response to two GH provocation tests and a modest increase of insulin-like growth factor-1 (IGF-1) to an IGF-1 generation test." (PMID 29537382, 2018). "In this report, we described a child referred to our Pediatric Endocrinology Department for a severe growth failure, in presence of low IGF-1 and IGFBP-3, but normal GH levels." (PMID 29025428, 2017). "We therefore advise stringent follow-up of growth, supplemented by IGF-1 concentrations, bone age determination, and (primed) GH stimulation tests in case of growth failure." (PMID 26840047, 2016). "Insulin like growth factor 1 (IgF1) and insulin like growth factor binding protein (IgFPB3) are in the low normal range in children with growth failure from different aetiologies." (PMID 27861527, 2016). "In children suffering from growth retardation, 5-month long OKG administration (15 g/day) induced growth acceleration in association with increased plasma IGF-1 level." (PMID 22578071, 2012). "The average serum IGF-1 SDS of these patients with growth failure was -1.58 ± 1.14." (PMID 33815276, 2021). "Furthermore, a partial deletion of the IGF-1 gene results in intrauterine growth failure and severe post-natal growth delays and intellectual disabilities." (PMID 24961618, 2013). "Other factors: Associated growth failure and pubertal delay may contribute to adverse bone health due to the absence of an anabolic effect of Insulin-like growth factor 1 (IGF-1) and sex hormones on bones." (PMID 37375708, 2023). "Among children with growth retardation, a statistically significant positive correlation was found between the adjusted Z-score Spine and both BMI SDS (r = 0.4) and IGF-1 SDS (r = 0.35)." (PMID 40364018, 2025). "Growth failure has been widely recognised as one of the consequences of OSAHS in children, with impairment of whole auxological parameters: height, weight, BMI and IGF-1 serum levels." (PMID 35655540, 2022). "Reduced circulating IGF-1 and growth failure were also reported in T1DM patients, while IGF-1 concentrations in renal tissue were shown to be increased, suggesting increased local synthesis and/or IGF-1 sequestration from the circulation." (PMID 34143299, 2021). "However, in patients with non-GH-deficient causes of growth failure, and initially normal IGF-1 SDS, elevated IGF-1 levels associated with higher GH doses may be required to achieve an acceptable height gain." (PMID 31284701, 2019). "Growth failure in CKD is not due to GH deficiency, although relative GH and/or IGF1 insensitivity may play a role." (PMID 39062256, 2024).
Parkinson disease (56 papers, 2009 to 2026). A progressive degenerative disorder of the central nervous system characterized by loss of dopamine producing neurons in the substantia nigra and the presence of Lewy bodies in the substantia nigra and locus coeruleus. "IGF-1 deficits also correlated with impaired cognition in other conditions, such as GH deficiency, Parkinson’s, or even in normal aging." (PMID 40141202, 2025). "In Parkinson’s disease, lower circulating levels of IGF-1 are associated with poor cognition, poor mood, and high anxiety." (PMID 38374201, 2024). "Dysregulation of the IGF-1 system has been associated with neurodegenerative diseases, such as Alzheimer’s, Parkinson’s, and Huntington’s disease." (PMID 38374201, 2024). "For example, in patients with early Parkinson’s disease (PD), low serum IGF-1 was associated with poor performance on cognitive tasks that assess executive function, attention, and verbal memory." (PMID 37638322, 2023). "We were therefore surprised to find that reducing insulin/IGF1 signaling augments the loss of ventral cephalic neurons in the Parkinson’s disease model." (PMID 29295479, 2017). "In addition, associations between IGF-1 and cognition also have been found in growth hormone deficient children and adults, children with infantile spasms, people with Parkinson's disease, Alzheimer, and delirium." (PMID 25114679, 2014). "In addition, associations between serum IGF-1 levels and cognitive function in patients with growth hormone deficiency, infantile spasms, Parkinson’s disease, and delirium were reported." (PMID 30294204, 2018). "Taken together, we conclude that, in our hands, insulin/IGF1 signaling, a modulator of aging, has indeed an effect—albeit opposite to what was expected, and cell-type specific—on the age-dependent loss of dopaminergic neurons in the C. elegans Parkinson’s disease model." (PMID 29295479, 2017). "The scientific reasoning for exploring GLP-1RAs in Parkinson’s disease is similarly strong, as PD is characterized by deficits in insulin/IGF-1 signaling, mitochondrial dysfunction, neuroinflammation, and the toxic accumulation of α-synuclein." (PMID 41356006, 2025). "The authors observed in human embryonic stem cells (hESCs)-derived embryoid bodies (hEBs), that BPA exposure-induced expression of IGF-1 insufficiency, and this IGF-1 expression can be related to inducing Parkinsonism." (PMID 37855918, 2024). "Linear associations between circulating insulin-like growth factor-1 (IGF-1) levels and Parkinson’s disease (PD) have been evidenced in observational studies." (PMID 38699559, 2024). "In the present study, we investigated the characteristics of IGF-1 in serum important for a valid and reliable biomarker in Parkinson's disease (PD)." (PMID 26967642, 2016). "In fact, IGF-1 resistance in the central nervous system (CNS) impairs neuroprotection in Alzheimer and Parkinson diseases." (PMID 27483352, 2016). "Initially, 35 studies were retrieved with MeSH words: “Parkinson’s disease” and “insulin-like growth factor-1”." (PMID 26657015, 2015). "Male sex was found to be the highest-ranking risk factor, closely followed by serum IGF-1, when the relative impacts of non-genetic variables in Parkinson’s patients were examined using a comprehensive machine learning algorithm (IDEARS)." (PMID 40933823, 2025). "In this study, patients with intermediate to severe Parkinson’s disease were examined for how Resagiline and levodopa and benserazide hydrochloride affected their motor performance, serum levels of homocysteine (Hcy), and insulin-like growth factor (IGF-1)." (PMID 37803329, 2023). "During the course of their illness, people with Parkinson’s disease may see changes in their insulin-like growth factor (IGF-1) and serum homocysteine (Hcy) indices." (PMID 37803329, 2023).
Parkinson disease (continued). "Since E2 mediates neuroprotective effects through IGF1‐IGFR signalling, we evaluated synergistic and antagonistic interactions between IGF1R genes and genes for neurodegeneration implicated in amyotrophic lateral sclerosis and Alzheimer's, Huntington's, Parkinson's and prion diseases." (PMID 37594177, 2023). "Furthermore, IGF-1 has been shown to stimulate cell survival pathways in vitro and in disease models such as subarachnoid hemorrhage, neonatal hypoxia ischemia hippocampal trimethytin toxicity and Parkinson’s disease." (PMID 24618563, 2014). "Insulin-like growth factor 1 (IGF-1) and epidermal growth factor (EGF) exert neuroprotective effects in Parkinson’s disease (PD)." (PMID 36383265, 2023). "The metabolite of IGF-1, cyclic glycine-proline, was found in blackberry anthocyanins; administration increased cyclic glycine-proline in the cerebrospinal fluid of patients with Parkinson’s disease, a condition with IGF-1 deficiency, but no clinical measurements were reported." (PMID 36615279, 2022). "Also, chronic inflammation potentiates resistance to insulin and insulin-like growth factor-1 (IGF-1) in the hypothalamus, as presented in Alzheimer’s and Parkinson’s disease." (PMID 37996797, 2023). "Because there are no longitudinal studies on IGF-1 in PD patients yet available, we defined the two different stages of Parkinson's disease as “early” and “moderate” PD." (PMID 26967642, 2016).
pulmonary fibrosis (54 papers, 2006 to 2025). Chronic progressive interstitial lung disorder characterized by the replacement of the lung tissue by connective tissue, leading to progressive dyspnea, respiratory failure, or right heart failure. "This suggests that the inhibitory effect of CDN on EMT is the core phenotypic effect underlying its alleviation of BLM-induced pulmonary fibrosis, and the molecular mechanism of this effect requires further validation through the IGF1/PI3K-AKT pathway." (PMID 41516127, 2025). "Additionally, miR-130b-3p is implicated in fibroblast regulation by targeting IGF-1 mRNA, which influences epithelial–mesenchymal interactions in lung fibrosis." (PMID 40699705, 2025). "This target has proven effective in bronchiolitis obliterans, idiopathic pulmonary fibrosis, and thyroid-associated ophthalmopathy, using rapamycin, sirolimus or an insulin-like growth factor-1 (IGF-I) receptor blocking antibody." (PMID 37494277, 2023). "This work provides the evidence that CDN alleviates BLM-induced pulmonary fibrosis by targeting the IGF1/PI3K/AKT-EMT axis." (PMID 41516127, 2025). "In contrast to these diseases, upregulated IGF-1 expression or signaling is observed in many fibrotic lung diseases such as idiopathic pulmonary fibrosis, late-stage sarcoidosis, and secondary fibrosis." (PMID 39220366, 2024). "IGF-1 plays a critical role in lung disease, like cancer and lung fibrosis; interestingly, the expression of IGF-1 in LC tissue was higher than in adjacent normal lung tissue." (PMID 39555455, 2024). "The expression of CTBP1 was detected by stimulating the cells with pulmonary fibrogenic cytokines (FCS, PDGF-BB, IGF-1, transforming growth factor –β1) to simulate the pulmonary fibrosis model." (PMID 37138491, 2024). "In the murine model of bleomycin-induced pulmonary fibrosis, we observed upregulation of Igf1, transient upregulation of Igfbp4 and downregulation of Igfbp6." (PMID 35741102, 2022). "While being an important survival factor for various cell types, IGF-1 has also been implicated in fibrotic disorders, including SSc, where serum IGF-1 levels are elevated in patients with more severe skin and lung fibrosis." (PMID 35052842, 2022). "The expression of α-SMA is another marker of pulmonary fibrosis, and blocking the IGF1 pathway in vivo has been reported to reduce α-SMA expression after injury." (PMID 33672678, 2021). "Insulin-like growth factor 1 (IGF1) is a pro‐fibrotic growth factor that stimulates fibroblast proliferation and collagen synthesis in idiopathic pulmonary fibrosis." (PMID 33746571, 2021). "Elevated serum IGF-1 level was reported in those with more severe skin involvement and pulmonary fibrosis in SSc patients." (PMID 33430962, 2021). "Sequential expression of IGF-1 and TGF-β was found to synergistically aggravate fibrosis, and upregulation of IGF-1 via TGF-β in myofibroblasts was documented in the fibrotic lung tissue in advanced idiopathic pulmonary fibrosis (IPF)." (PMID 33430962, 2021). "Considering the important role of the IGF1/PI3K/AKT signaling pathway in inducing AECs senescence in pulmonary fibrosis, determining the mechanisms that regulate this signaling pathway is imperative." (PMID 34329195, 2021). "In bleomycin-induced lung injury mouse models, IGF-1 mRNA was significantly increased in pulmonary fibrosis, and IGF-1 overexpression exacerbated the fibrotic process." (PMID 33430962, 2021). "Pulmonary fibrosis is associated with increased IGF-1 originated from AMs, and IGF-1 can stimulate the differentiation of fibroblasts into myofibroblast phenotypes, thus playing an important role in pulmonary fibrosis." (PMID 32793225, 2020). "Fra-2/AP-1 contribute to pulmonary fibrosis in IPF and animal models of pulmonary fibrosis, possibly through activation of profibrotic signals, including IGF-1." (PMID 30018981, 2018).